EGFR (epidermal growth factor receptor)
Diseases named in the same sentence as EGFR in open-access papers (continued):
Sharing a sentence is not in itself a finding about the gene and the disease.
cancer (continued). "EGFR activation in cancer cells can upregulate PD-L1 through the MAPK signaling pathway that leads to increased activity of ERK1/2 and AKT which facilitate cell proliferation and invasion." (PMID 40809430, 2025). "Given the importance of these pathways for cancer cell survival, EGFR has emerged as a valuable target in the treatment of mCRC." (PMID 40149618, 2025). "Gefitinib is a competitive, reversible inhibitor of the tyrosine kinase domain of the EGFR, which disrupts the signaling in cancer cells with mutant or overactive EGFR." (PMID 41199076, 2025). "To investigate the relationship between EGFR and cancer cell immunotherapy response, we included two scRNA-Seq ICI cohorts with clear clinical outcomes from the GEO database." (PMID 40574864, 2025). "Regarding cancer treatment strategy, blocking EGFR leads to RAS/RAF/MEK and PI3K/AKT/mTOR signaling cascade suppression." (PMID 40056327, 2025). "Overexpression of EGFR was first recognized in various cancers in the late 1980s and later identified to be an oncogenic driver mutation in NSCLC, along with other cancers." (PMID 39941723, 2025). "Since activation of EGFR regulates signaling network and affect cancer cell proliferation, migration and apoptosis, EGFR and related proteins have become effective targets for cancer treatment." (PMID 39891180, 2025). "The epidermal growth factor receptor (EGFR) on cancer cells is the target of another therapeutic approach." (PMID 40136714, 2025). "FBXW2 has been reported to reduce expression of several proteins associated with malignant tumor states, such as β-catenin, SKP2, NF-κB p65 and EGFR, which contribute to cancer stemness, tumorigenesis and metastasis." (PMID 40721413, 2025). "Other pathways include Rab31, which improves the exosomal packaging of the epidermal growth factor receptor (EGFR) in cancer cells, and Ceramide, which promotes ILV budding." (PMID 40530018, 2025). "The APC in this experiment was a PC3 cancer cell highly expressing EGFR on its cell surface; this cell was targeted by an anti‐EGFR FabH binding through the GLM arm." (PMID 39865354, 2025). "Additional preclinical data indicate that cancer-associated fibroblasts (CAF), through the secretion of various soluble factors, play a central role in inducing resistance to EGFR blockade." (PMID 40940901, 2025). "It has been reported that EGFR expression was detected in 44.7% of cancer tissues compared to 21.4% in normal tissues." (PMID 40236691, 2025). "Looking specifically at the acquired drug resistance of EGFR tyrosine kinase inhibitors (TKIs) in NSCLC, it has been shown that inhibition of NF-κB is sufficient to reduce the viability of cancer cells that have adapted to EGFR TKIs." (PMID 41305005, 2025). "SLC16A6 expression increased by 1.4-fold in A549 and 2.3-fold in NCI-H1975, indicating that metabolic shifts under PM2.5 stress are more pronounced in EGFR-mutant cancer cells." (PMID 40559957, 2025). "The epidermal growth factor receptor (EGFR) is a key target for both cancer diagnosis and therapeutic interventions." (PMID 40906195, 2025). "As anti-cancer activity via signal condensation highly depends on the EGFR expression levels in target cells, these NPs exhibit negligible cytotoxicity in normal cells." (PMID 41140511, 2025). "This synergism has significant anti-cancer effects on pancreatic ductal adenocarcinoma via targeting EGFR-signaling through Laminin subunit beta 3 (LAMB3) regulation." (PMID 40490812, 2025).
cancer (continued). "The largest number of disease/pathway links was found for the apoptosis-mediating FAS (n = 52) and for two cancer-related proteins, EGFR (n = 43) and ERBB2 (n = 39)." (PMID 40593564, 2025). "Our focus on cancer was on several pathways including EGFR/KRAS signaling, cyclin-dependent kinases, aromatase hormonal treatment therapy, and epigenetics involving DNMT and HDAC." (PMID 40141193, 2025). "As a result, there has been a boom in research into the design and synthesis of EGFR inhibitors, sparked by accumulating evidence that they hold substantial potential in cancer treatment." (PMID 38739230, 2025). "For instance, EGFR-specific TKIs have been found to trigger a comprehensive interferon response in cancer cells, thereby affecting the mobilization and participation of immune cells in the treatment response." (PMID 39788945, 2025). "By simultaneously targeting CDK2, EGFR, and Tubulin, this multi-targeted therapy addresses multiple pathways involved in cancer cell survival, proliferation, and metastasis." (PMID 40526618, 2025). "In summary, these findings provide an important reference for future studies on the regulatory mechanism of Hub-EGFR.Sig in cancer immunotherapy." (PMID 40574864, 2025). "Among the panel of cancer biomarkers, the epidermal growth factor receptor (EGFR) stands as one of the most frequently overexpressed receptors in different cancer types." (PMID 39940134, 2025). "MA exerts its anticancer effects by targeting key proteins such as EGFR, SRC, HSP90AA1, MDM2, and IGF1R, which are often overexpressed or mutated in resistant cancer cells." (PMID 40070571, 2025). "This fluorescence recovery serves as a significant indicator of the presence of EGFR on the cancer cell surface, highlighting the potential of this system for targeted cancer diagnostics and therapeutic applications." (PMID 40368641, 2025). "It has been reported that PHA-665752 works in synergy with erlotinib, an EGFR inhibitor, to decrease the viability of cancer cells." (PMID 39859448, 2025). "To analyze their in vivo anti‐cancer mechanisms, we performed western blot assays to evaluate the EGFR degradation effect and HDAC inhibition on lung tumor tissues." (PMID 40842076, 2025). "CBLC belongs to the CBL family and is an E3 ubiquitin ligase involved in EGFR ubiquitination and degradation, widely upregulated in various cancers, including NSCLC, hinting at its oncogenic potential." (PMID 40766337, 2025). "Mitochondrial priming is a key indicator of cancer cell response to EGFR inhibition as it is with other survival kinase inhibitors used in treating solid tumors." (PMID 40507334, 2025). "Ultimately, this can pave the way for the design of more effective and safer EGFR inhibitors, enhancing the overall quality of life for patients battling cancer." (PMID 41488515, 2025). "ALYREF binds to m5C‐modified epidermal growth factor receptor (EGFR) mRNA and promotes cancer growth by stabilizing EGFR mRNA, upregulating EGFR expression and enhancing the STAT3 signaling pathway." (PMID 40448344, 2025). "Using multiple ML algorithms based on interactive analysis of scRNA-Seq and bulk RNA-Seq data, we successfully devised an improved predictive biomarker for immunotherapy and identified Hub-EGFR.Sig to explore the heterogeneity of different cancer prognoses." (PMID 40574864, 2025).
cancer (continued). "The 5 most cited ENT studies examined inhibition of ROS scavengers in cancer stem cells with buthionine sulfoximine, nimorazole, EGFR inhibitors, cisplatin, and beta - 1 Integrin inhibitors." (PMID 40667051, 2025). "Significant T cell-surface decoration with EGFR-LiTE persisted for 4 days in vitro, indicating that, despite the transient nature of mRNA, engineered T lymphocytes remain armored to attack cancer cells for several days." (PMID 41341587, 2025). "Because the incidence and severity of EGFR inhibitor-related skin toxicities correlate with treatment outcomes, management during the treatment period is essential for cancer control." (PMID 40888993, 2025). "EGFR makes for an attractive target for HNSCC due to its high expression in these cancers, however as this receptor is also expressed in normal epithelial cells, there is a need to mitigate its potential toxicities when targeted by an ADC." (PMID 40868227, 2025). "Ultimately, this highly specific treatment strategy that includes cancer‐specific target gene SOX2 with functional anti‐EGFR tLNPs holds great promise for safe and efficient CRISPR treatment HNC, and ultimately for many other palpable solid cancers." (PMID 39736115, 2025). "Previous studies have shown that amlodipine exerts anti-cancer effects by inhibiting EGFR phosphorylation." (PMID 41145413, 2025). "This study identified DDAH1 as a prognostic marker and a potential therapeutic target for nimotuzumab to overcome treatment failure and chemoresistance in LANPC and other EGFR‐positive cancers." (PMID 40538138, 2025). "Aside from this study, the EGFR glycosylation and phosphorylation have been characterized in other cancer types." (PMID 40154885, 2025). "Protein–protein interaction networks identified hub genes for each cancer type, with key shared targets including EGFR, ESR1, PTGS2, and STAT3." (PMID 41155677, 2025). "We found that EGFR was the core stemness-responsive driver gene by pseudotime analysis and gene interaction analysis, suggesting that EGFR can mediate radiation-induced stemness activation in cancer cells." (PMID 40003899, 2025). "EGFR-TKI resistant cancer cells upregulate miR-21, leading to reduced pro-inflammatory cytokine release, hindering CD8+ T cell migration and impacting T cell differentiation." (PMID 40058234, 2025). "As a result, targeting the EGFR signaling pathway in different cancer cells and discovering suppressive agents are important." (PMID 40172364, 2025). "High levels of IGF-1R can cause resistance across different cancers, and cancer cells can become resistant to IGF-1R inhibitors, by activating PI3K/mTOR pathways through alternative EGFR signaling." (PMID 41427337, 2025). "The combination of emodin and EGFR inhibitor synergistically inhibits cancer cell proliferation in vitro and in vivo, modulating STAT3 protein expression." (PMID 40490812, 2025). "The combination thus targets complementary vulnerabilities, providing a strong rationale for its use in EGFR-independent cancers." (PMID 41401147, 2025). "In the near future, modulators of the EGFR/RAS/MYC axis are likely to become effective therapeutic tools for treating cancer, particularly in cases where existing therapies are unsuccessful." (PMID 39858030, 2025). "This study presents Cy3‐AptEGFR@BPNSs, a novel nano‐detector for real‐time, visual monitoring of EGFR expression in cancer cells." (PMID 40368641, 2025). "Tyrphostin (AG1478) is a selective EGFR inhibitor that disrupts EGFR autophosphorylation and signaling in cancer, including GB, inhibiting cell migration and invasion." (PMID 40191718, 2025). "Cancer progression is intimately tied to EGFR TK signal transmission, therefore blocking receptor activation can effectively stop tumor growth." (PMID 40395767, 2025).
cancer (continued). "Overexpression of EGFR has been observed in a variety of cancers, allowing the binding of sufficient small molecule Gd-based contrast agents to generate robust contrast enhancement and to overcome the low sensitivity of MRI." (PMID 41325799, 2025). "In our cohort, most cases contained cancer-specific SNV/indel mutations, primarily KRAS and EGFR variants with significant clinical importance, with fewer instances of other variants." (PMID 40282516, 2025). "These NPs, called HB-AuNPs, are targeted to cancer cells overexpressing epidermal growth factor receptor (EGFR) and ErbB2." (PMID 41048541, 2025). "In the recent decades, EGFR-targeted therapies have been recognized as the master orchestrator in regulating epithelial transformation and the behavior of cancer cells." (PMID 40329373, 2025). "The EGFR signaling pathway assumes a pivotal role in oncogenesis and the progression of cancer, with its hyperactivity exhibiting a correlation with advanced stages and diminished survival rates in BC." (PMID 40575382, 2025). "This type of approach relies on the presence of ligands that recognize specific receptors, including EGFR, which are overexpressed on the surface of cancer cells." (PMID 39940134, 2025). "To further explore the relationship between EGFR.Sig and the effect of cancer immunotherapy, we comprehensively analysed the correlation between EGFR.Sig and 75 immune-related genes previously published in the pan-cancer TCGA cohort." (PMID 40574864, 2025). "The situation with EGFR and TKIs is just a representative example of the challenges faced for a broad range of cancers and therapeutics." (PMID 39533106, 2025). "Because of the high affinity between the EGFR aptamer and EGFR, Cy3‐AptEGFR@BPNSs accurately identifies EGFR on cancer cells, enabling visualisation through fluorescence labelling." (PMID 40368641, 2025). "Functional profiling shows that the most active compounds suppress EGFR activation in human cancer cell line models." (PMID 40665765, 2025). "The use of anti-EGFR monoclonal antibodies to target cancer cells provides specific binding to the extracellular domain of EGFR, blocking ligand binding." (PMID 40438187, 2025). "Cancer cells can develop chemoresistance by altering key signaling cascades, notably the EGFR/PI3K/PTEN/Akt/mTOR axis." (PMID 41303548, 2025). "Neoantigen vaccines are under investigation for various cancers, including epidermal growth factor receptor (EGFR)-driven lung cancers." (PMID 39972134, 2025). "Out of this series of 270 patients with a definitive diagnosis of cancer, molecular testing was carried out on 142 patients, looking for epidermal growth factor receptor (EGFR), anaplastic lymphoma kinase (ALK), c-ros oncogene 1 (ROS1) and PD-L1 mutations." (PMID 39941279, 2025). "The pathways ranked top 20 of KEGG were screened out, and that mainly related to proteoglycans in cancer, prolactin signaling pathway and EGFR tyrosine kinase inhibitor resistance." (PMID 40427433, 2025). "Alterations in CBL and MAPK3 reflect a balance of signaling pathways involved in cancer cell growth and survival, particularly the EGFR/MAPK pathway, which plays a key role in stimulating cell proliferation, evading apoptosis, and metastasis." (PMID 41226554, 2025). "This pattern suggests that KRAS mutation carriers, who typically respond poorly to TKI intended for EGFR/ALK-positive cancers, often receive chemotherapy or radiation." (PMID 40502411, 2025). "As expected, Hub-EGFR.Sig presented stable enrichment scores across multiple cancer types, of which LUAD, LUSC and BLCA showed higher scores." (PMID 40574864, 2025). "Since all OTSCCs were shown to have elevated EGFR levels, this cancer type is particularly attractive for research into potential novel treatments that target the EGFR receptor." (PMID 41007319, 2025).
cancer (continued). "The EGFR-epicatechin gallate and 1-O-galloyl-beta-D-glucose-AKT1 complex have widespread interaction with cancer-associated targets, while others have fewer interactions." (PMID 40573291, 2025). "Together, our study pinpoints the PRMT1 isoform as a critical vulnerability of cancer persistence in EGFR- or KRASG12C-targeted therapies." (PMID 39699269, 2025). "For example, the identification of genetic mutations, such as those in the EGFR gene for lung cancer or BRCA1/2 for breast cancer, can provide early signals of cancer risk or the presence of cancer at a molecular level, often before physical symptoms appear." (PMID 40277534, 2025). "Specific mutated genes began to be identified in the blood of cancer patients in the form of ctDNA about 20 years ago, including KRAS and PIK3CA in patients with colorectal cancer, EGFR in breast cancer patients and in NSCLC patients." (PMID 41294857, 2025). "EGFR amplification has been implicated in squamous carcinogenesis across HPV-associated head and neck and anogenital cancers." (PMID 40979503, 2025). "In contrast, KI exposure did not affect EGF transcript levels; however, it did reduce EGFR1 expression (here referred to as EGFR) in cultured murine WR21 cancer cells." (PMID 40508009, 2025). "The epidermal growth factor receptor (EGFR) plays a crucial role in cancer and is often targeted for both diagnosis and treatment." (PMID 40906195, 2025). "EGF-immobilized gold nanoparticles (NPs) serve as a new candidate for anti-cancer drugs targeting EGFR." (PMID 41140511, 2025). "Many cancers exhibit the overexpression of proteins such as HER2 in breast cancer or EGFR in lung cancer." (PMID 41180630, 2025). "EREG is highly expressed in various cancers, primarily activating the EGFR signaling pathway and promoting cancer progression." (PMID 39883700, 2025). "Alternative targets are needed for cancers that either lack EGFR expression or exhibit low levels of EGFR." (PMID 40792441, 2025). "A generally correlation between EGFR.Sig and most of the immune-related genes across 30 different cancers was observed." (PMID 40574864, 2025). "In conclusion, our study underscores the importance of the combined targeting of RET and EGFR to overcome resistance mechanisms in RET-rearranged cancers." (PMID 40405293, 2025). "Best evidence summary for management of epidermal growth factor receptor inhibitor-induced skin toxicity symptoms in cancer patients." (PMID 41377804, 2025). "Among the gene mutations that significantly co-occurred with copy number amplifications (CNAs), two genes showed association in multiple cancer types: NOTCH3 in BRCA and LUAD, and EGFR in LGG and LUAD." (PMID 41415395, 2025). "Specifically, while preserving a similar treatment efficacy, CAP circumvented the side effects accompanied with EGFR inhibitors by activating EGFR that rendered cancer cells vulnerable to ferroptosis." (PMID 39781456, 2025). "It is known that ROS are involved in numerous signal transduction pathways in cancer cells, including p14ARF tumor suppressor and EGFR." (PMID 40573248, 2025). "Plasma-based NGS using a panel of 825 cancer-related genes (Genetron Health; Beijing, China) indicated the presence of EGFR 19del (p.L747_T751del) (VAF: 3.4%), EGFR T790M-cis-C797S (VAF: 0.1%), and EGFR T790M (VAF: 1.9%)." (PMID 40843372, 2025). "The three studies examined the efficacy of combining EGFR-TKI with TCM in patients with cancer, with PFS as the primary endpoint." (PMID 40535810, 2025). "Our findings suggest potential clinical applications for enhancing treatment efficacy in EGFR-mutant cancers." (PMID 39747003, 2025). "Third, the broader applicability of the agrin‐EGFR‐YAP/TAZ axis in other cancer types, particularly those with high EGFR expression or activation, warrants exploration." (PMID 40165020, 2025). "The crucial physiological functions of EGFR and the adverse reactions induced by targeting EGFR highlight the complexity of targeting this receptor in cancer treatment." (PMID 39813112, 2025).